CD4 (CD4 molecule)
Diseases named in the same sentence as CD4 in open-access papers (continued):
Sharing a sentence is not in itself a finding about the gene and the disease.
malaria (continued). "There were 700 pregnant women with a CD4 cell count of at least 500 cells/μL who were included in the sensitivity model to assess the association between study time period and occurrence of malaria." (PMID 24363547, 2013). "In a prospective cohort study in South Africa, HIV-infected individuals with a CD4 cell count <200/μl had an increased risk of severe malaria (odds ratio 4.8)." (PMID 23941258, 2013). "Subjects with low CD4 counts were at higher risk of infections and helminth infection is a risk factor for malaria." (PMID 23967365, 2013). "Another study also showed that acute malaria is associated with an increase in viral load and a decrease in CD4+ cell count, but this generally returns to pre-infection levels a few weeks after successful malaria therapy." (PMID 23327493, 2013). "Overall, our finding demonstrated that APFP is highly prevalent in regions endemic for malaria in southern Mozambique and was associated with lower hematological parameters but unaltered lymphocyte counts, CD4+ and CD8+ T cells counts." (PMID 23710648, 2013). "All recorded events, with the notable exception of malaria, and unfavorable outcomes (death and loss to follow-up) were significantly more frequent in patients with a CD4 count <100/mm3 and occurred within the first year following ART initiation." (PMID 24373303, 2013). "With regard to malaria, we found that a low CD4 count was associated with an increased number of malaria episodes." (PMID 23967365, 2013). "HIV-positive pregnant women who had lower CD4 cell counts were more at risk of being infected by intestinal worms and malaria." (PMID 23967365, 2013). "Studies about countries where malaria is endemic suggest that the patients with a low CD4 T cell count or advanced HIV-1 disease had an increased risk of malaria events, higher parasitaemia and more severe clinical episodes." (PMID 22540214, 2012). "The main effects (i.e. without considering an interaction) of IFNγ-IL2+TNF−, IFNγ-IL2+TNF+, and IFNγ-IL2-TNF+ CD4+ T cells were reductions in the risk of clinical malaria of varying statistical significance." (PMID 23300801, 2012). "Multiple comparisons (i.e. 18) have been undertaken to identify the association between TNFα producing CD4+ T cells and protection from clinical malaria." (PMID 21998698, 2011). "TNFα and IFNγ producing CS-specific CD4+ T cells were at much lower frequencies among control vaccinees, but nevertheless were associated with reduced risks of clinical malaria of borderline significance." (PMID 21998698, 2011). "On applying the fourth of the Prentice criteria, we found that vaccination group was still an independent predictor of clinical malaria risk in a multivariable model including CD4+ TNFα+ cells (HR = 0.69, 95%CI 0.48–0.97, p = 0.036)." (PMID 21998698, 2011). "In a multivariable analysis TNFα+ CD4+ T cells were independently associated with a reduced risk for clinical malaria among RTS,S/AS01E vaccinees (HR = 0.64, 95%CI 0.49–0.86, p = 0.002)." (PMID 21998698, 2011). "On ICS, IFNγ production by CS-specific CD4+ T cells was associated with a reduced risk of clinical malaria of borderline significance (p = 0.07)." (PMID 21998698, 2011). "Multivariate analysis showed a significant association between increased CD4+ CD25high numbers in peripheral blood and increased risk of clinical malaria." (PMID 20442856, 2010). "Pre-ART CD4 count below 10 cells/mm3, younger age and less education correlated with a higher malaria risk, while cotrimoxazole prophylaxis lowered the risk." (PMID 20519024, 2010). "The increased risk for uncomplicated malaria in HIV-1–infected patients with a low CD4 count is consistent with information in several cohort studies." (PMID 19402961, 2009). "Lastly, individuals with higher numbers of CD4+CD25high T cells were significantly associated with increased susceptibility to malaria." (PMID 18446217, 2008).
malaria (continued). "Higher numbers of CD4+ CD25high T cells, potentially regulatory T cells, were associated with a significantly increased risk of clinical malaria (p = 0.039)." (PMID 18446217, 2008). "Multivariate analysis of the possession CD4+CD25high T cells showed a significant association with increased malaria incidence (p = 0.039)." (PMID 18446217, 2008). "Asymptomatic malaria has been shown to be associated with a decreased percentage CD4+ count in 3–6 year old West African children." (PMID 18462487, 2008). "HIV-1 infected adults have a higher risk of malaria infection, clinical malaria and treatment failure and this is inversely related to the absolute CD4 cells count." (PMID 16923176, 2006). "Additionally, NK cells have been implicated in malaria immunity, especially in early-stage infections before CD4+ T cell activation; research in malaria-endemic areas indicates that NK cell activation takes place early in the infection process." (PMID 41154861, 2025). "Additionally, CD4+ cytotoxic T-cell associated IFN-γ production was linked to protection against malaria." (PMID 38049509, 2024). "The malaria patients again showed considerable haematological alterations in lymphocyte sub-sets and the parasite density appeared to be strongly associated with CD4 + T-cell reduction." (PMID 38987710, 2024). "As an evidence of these effects, P2RX7 is upregulated in CD4+ T cells activated during acute murine malaria caused by Plasmodium chabaudi and promotes membrane pore formation, intense Ca++ influx and IL-2 production, and thus induces a vigorous Th1 response that protects mice from death." (PMID 36993971, 2023). "Thus, diverse MBCs expressing low chemokine receptor levels and a CD4+ TH2 cell bias were associated with reduced odds of clinical malaria." (PMID 35475529, 2022). "On the other hand, the suppression of joint swelling upon coinfection could be linked to the dysregulation of virus-specific CD4 T-cell responses, main drivers of joint inflammation at 6 dpi by malaria." (PMID 35039441, 2022). "Therefore, possible involvement of the ICOS dependent regulatory CD4+ICOS+Foxp3+ T cells in resistance/susceptibility during malaria parasite is explored in this study." (PMID 35109868, 2022). "Whether the Tr1-like cells are bona fide Tr1 cells instead of Th1 cells expressing IL-10 remains to be seen, but regardless, the IL-10-producing CD4+ T cells in malaria limit disease-associated pathology and may contribute to clinical immunity." (PMID 36389662, 2022). "However, severe malaria has repeatedly been reported to cause a decline in CD4+ T cell counts and induction of anemia through CD8+ T cell-dependent plasmodial clearance and red cells removal in the Spleen." (PMID 35223394, 2021). "If TGF-β signaling promotes Treg expansion during malaria, this could function to suppress excessive inflammation caused by unchecked CD4 TH1 and IFN-γ responses." (PMID 32043415, 2020). "However, some studies in malaria endemic regions have reported the risk of malaria to be higher in patients with low CD4 cell counts which is the most probable explanation of what is observed in this study." (PMID 33175844, 2020). "From this study however, it is unclear whether the low CD4 is the risk factor or the effect of having the malaria parasites." (PMID 33175844, 2020). "Indeed, higher blood parasitemia levels are associated with higher frequencies of CD4+Foxp3+ Tregs in humans and mice with malaria." (PMID 30915078, 2019). "This becomes imperative in the HIV/AIDS era because HIV is a major risk factor for TB reactivation by depleting CD4 cells, and malaria/TB/HIV triple infection could worsen the immune suppression." (PMID 31428162, 2019). "To this end, we assessed the expression pattern of co-inhibitory molecules and other molecules implicated in regulatory capacity on CD4+ T cells between children with complicated malaria, uncomplicated malaria, asymptomatic Pf infections, and a non-infected control group." (PMID 29555909, 2018).
malaria (continued). "Thus, different CD4+ T cell phenotypes are associated with complicated versus uncomplicated malaria, suggesting a two-sided role of CD4+ T cells in malaria pathogenesis and protection." (PMID 29555909, 2018). "Polyfunctional analysis of the ICS data of the later study showed that IFN-γ-IL-2−TNF-α+ CD4+ T cells independently predicted reduced risk of clinical malaria, although the response was also detected in control vaccinees, and found a synergistic interaction with anti-CSP IgG titers." (PMID 28878775, 2017). "Both γδ T cells and CD4+ T cells have been implicated in immunity and tolerance to malaria." (PMID 28821806, 2017). "In our cohort, it was specifically monofunctional IL10 CD4 T cells that were associated with a reduced risk of symptomatic malaria following Pf infection; high frequencies of these cells were significantly associated with reduced odds of symptomatic malaria when infection." (PMID 29097996, 2017). "On the other hand, CD4 T cells also contribute to malaria‐associated pathology." (PMID 28935714, 2017). "We identified an important transcriptional regulator called B lymphocyte-induced maturation protein 1 (Blimp-1), which promotes IL-10 production by IFNγ-producing CD4+ T (Tr1) cells during malaria and visceral leishmaniasis, two important diseases caused by protozoan parasites." (PMID 26765224, 2016). "Decreased CD4 counts have been associated with higher risk of acquiring malaria." (PMID 27417903, 2016). "The expansion of this CD38+ CD4+ T population following infection and its significant association with reduced blood-stage parasite burden is consistent with an important functional role for these cells in protective immunity to malaria in humans." (PMID 27662621, 2016). "Using cord blood samples from a cohort of mother-infant pairs followed from early in pregnancy until delivery, flow cytometry analysis was completed to assess the relationship between pregnancy-associated malaria and fetal cord blood CD4 and dendritic cell phenotypes." (PMID 27717402, 2016). "Finally, this global analysis allowed for verifying that recurrent malaria is associated with a particular biomarker profile, characterized by decreased levels of the CD4+ and CD8+ T-cells along with a significant increase in the IL-10 production." (PMID 27581163, 2016). "CD4+ T follicular helper (Tfh) cells and their associated cytokines, such as IL-21, and germinal centre (GC) B-cells are critical mediators of humoral immune responses in many systems, and appear to be similarly important during experimental malaria." (PMID 27812214, 2016). "CD4+ T cells producing other cytokines such IL-2, IL-10 and IL-4 alone or in combination with the studied cytokines have been shown to be associated with protection from malaria." (PMID 27165269, 2016). "It is also unclear whether decreased CD4 counts would be associated with an increased risk of malaria in individuals on CTX prophylaxis." (PMID 27417903, 2016). "Whereas cell mediated immunity is believed to have a modest effect on the development of naturally acquired resistance to malaria, some studies have reported loss of memory or activated CD4+ T-cells, B cells and plasma cells after primary acute malaria episodes." (PMID 25906165, 2015). "There was a significant positive correlation between plasma neopterin levels and the percentage of HLA-DR + CD38 + CD4+ T cells during the malaria phase (P = 0.002; r = 0.493), suggesting that the activation of CD4+ T cells was associated with higher concentrations of neopterin induced by malaria." (PMID 25487036, 2014). "We hypothesized that CD4+ T cells producing the pro-inflammatory cytokines IFNγ and/or TNFα are associated with protection from malaria, and that T cell production of the regulatory cytokine IL-10 may interfere with the acquisition of protection." (PMID 24415936, 2014).
malaria (continued). "The loss of CD4+ T cells during malaria was perhaps first suggested when up to 99% of parasite-specific T cells labeled with the fluorescent dye 5-(and -6)-carboxy-fluorescein succinimidyl ester (CSFE), were found to be deleted only following infection of mice." (PMID 24904561, 2014). "We wondered whether the phenotype of CD4+ T cell responses to DBLα-tags to which a child had been exposed was associated with protection from future malaria episodes." (PMID 24453249, 2014). "A study of 112 subjects in Kenya (infants to adults) found a correlation between the frequency of CD4+CD25hi T cells and increased risk of clinical malaria, suggesting Tregs may negatively affect natural immunity to malaria in humans." (PMID 25309517, 2014). "HIV-infected women tend to experience faster CD4 decline during and after pregnancy, and could therefore be even more susceptible to helminth infection and malaria." (PMID 23967365, 2013). "All these T cells phenotypes were individually associated with reductions in the risk of clinical malaria, but IFNγ-IL2-TNF+ CD4+ T cells independently predicted reduced risk of clinical malaria on multi-variable analysis (HR = 0.29, 95% confidence intervals 0.15–0.54, p<0.0005)." (PMID 23300801, 2012). "In the blood stage malaria caused by the rodent parasite, Plasmodium chabaudi, the spleen CD4+ T cell population expands quickly, secretes considerable amounts of interferon-γ (IFN-γ) and helps B cells to produce high quantities of polyclonal immunoglobulin (Ig) M and IgG2a." (PMID 22272258, 2012). "We have now conducted a further analysis of the flow cytometry (FACS) data using alternative software to identify polyfunctional CD4+ T cell responses, and tested for the associations of T cell phenotype with protection from clinical malaria in Kenyan children vaccinated with RTS,S/AS01E." (PMID 23300801, 2012). "However, IFNγ-IL2-TNF+ CD4+ T cells were independently associated with protection against clinical malaria, and were induced by natural exposure." (PMID 23300801, 2012). "However, data from both experimental murine and human malaria show loss of activated or memory CD4+T cells, B cells and plasma cells and short-lived malaria-specific antibodies after a primary acute infection." (PMID 21687602, 2011). "The possibility that CD4+ T cells are implicated in this process is suggested by the fact that IL-10 or TGF-β deficiency intensifies the clinical signs in mice suffering from malaria." (PMID 21814579, 2011). "Indeed, a borderline statistical correlation between TNFα+ CD4+ T cells and a reduced risk of clinical malaria was observed among control vaccinees." (PMID 21998698, 2011). "After vaccination with RTS,S/AS01E, an increasing frequency of TNFα producing, CS-specific CD4+ cells detected using ICS was associated with a reduced risk of clinical malaria (HR = 0.64 for each 10 fold increase in the frequency of CD4+ TNFα+ T cells, 95%CI 0.49–0.86, p = 0.002)." (PMID 21998698, 2011). "The frequency of CD4+ TNFα+ T cells on ICS was associated with protection from clinical malaria." (PMID 21998698, 2011). "Therefore, immunosuppression is likely an additional risk, but absolute CD4 count cannot be interpreted during a severe malaria episode." (PMID 19402961, 2009). "The initial univariate analyses of the relationship between immune response and malaria, showed a tendancy for cultured TRAP response (p = 0.13) and CD56dim population (p = 0.076) to be associated with less malaria, and for CD4+ CD25high cells with increased malaria (p = 0.079)." (PMID 18446217, 2008). "In addition, we identified clusters that might be responsible for the reported association of CD4+ and γδ T cells with vaccine-induced immunity to malaria." (PMID 38716733, 2024).
malaria (continued). "Taken together, we have shown the association of cytokine-producing CD4+ T cells in naturally acquired immunity and its correlation with anti-malarial antibodies, which might synergize to mediate the control of blood-stage malaria parasites." (PMID 35922467, 2022). "In contrast to the protection against clinical malaria associated with this type of IL10-producing CD4+ T cells, protection against infection was governed by a different CD4 response profile, but both types of protection are considered part of the naturally acquired immunity against malaria." (PMID 34684226, 2021). "Low CD4 levels in the blood may increase an individual’s susceptibility to malaria." (PMID 34688312, 2021). "Most of the study participants experienced improvements in CD4 counts from baseline to post-treatment days 28 and 42, hence, baseline CD4 count was not a good marker of status of immunity in the post-treatment period when people were susceptible to malaria re-infections." (PMID 31126288, 2019). "Thus, in malaria-naive volunteers, reduced parasite burden during primary blood-stage P. falciparum infection was associated with the expansion of a specific subset of CD4+ T cells expressing the activation marker CD38." (PMID 27662621, 2016). "In malaria, epitope identification is particularly challenging, as more than 5000 proteins are encoded by the genome, which could generate hundreds of thousands of possible CD4+ T cell epitopes." (PMID 26858717, 2016). "However, whether this delayed acquisition of P. falciparum-specific IFN-γ-producing CD4+ T cells leads to higher risk to malaria disease remains unknown and warrants further investigation." (PMID 27165269, 2016). "We observed a strong positive correlation between P. falciparum-specific CD4+ T cell proliferation and the duration since last clinical episode of malaria (Spearman’s Rho = 0.34, P = 0.04) in continually exposed children, with more recent malaria associated with lower CD4+ T cell proliferation." (PMID 27660116, 2016). "Consequently it may be expected that the risk of malaria will decrease as individuals’ CD4 counts increase on ART." (PMID 27417903, 2016). "More recently, Gitau and colleagues described malaria-specific co-production of IFNγ and IL-10 following stimulation of CD4+ T cells with a variety of expressed PfEMP variants, although these co-producing cells represented a minor fraction of the total antigen-specific CD4+ T cell response." (PMID 24415936, 2014). "CD4+ cell activation associated with malaria may persist despite therapy." (PMID 23327493, 2013). "If TNFα producing CD4+ T cells are causally related to protection, they should be associated with protection whether they are acquired by vaccination or by natural exposure to malaria parasites." (PMID 21998698, 2011). "During both experimental and human malaria, there is evidence for loss of memory or activated CD4+ T cells, B cells and plasma cells and short-lived malaria specific Abs after a primary acute infection, suggesting that some of the components contributing to the humoral response may be short-lived." (PMID 20011127, 2009). "Our co-culture system may well reflect the processes occurring in vivo during malaria-infection, and explain the elevated levels of CD4+CD25hiFoxp3+ T cells observed in malaria-infected individuals and the association of IL-10, TGFβ and IL-2 with their induction." (PMID 19680449, 2009). "According to the WHO 2021 guidance, CTX should be provided to all PHW with a CD4 cell count of less than 350 cells/mm3 or clinical stage 3 or 4 disease, or in settings with high prevalence of malaria or severe bacterial infection." (PMID 40158188, 2025). "Children with uncomplicated malaria at 4 weeks of recovery had lower levels of CM CD4+CD45RA−CCR7+ compared to community controls (9.4% vs 13.7%)." (PMID 41285032, 2025).